TREM1 (triggering receptor expressed on myeloid cells 1)
Diseases named in the same sentence as TREM1 in open-access papers (continued):
Sharing a sentence is not in itself a finding about the gene and the disease.
colitis (continued). "When colonic LP cells of n = 9 mice of both groups were systematically analysed at 12–13 days post colitis induction, substantially reduced numbers of various cell subsets could be seen in Trem1−/− x Rag2−/− mice." (PMID 24453980, 2014). "Moreover, in the T cell-transfer and DSS-induced models of colitis, TREM-1 KO mice displayed a significantly attenuated disease, associated with reduced inflammatory infiltrates and diminished expression of pro-inflammatory cytokines." (PMID 25347935, 2014). "Although by the use of these agents substantial protection from endotoxin-induced shock, microbial sepsis or experimental colitis could be conferred, several aspects regarding the true biological role of TREM-1 remain unclear." (PMID 24453980, 2014). "However, it has also been reported that a TREM-1-antagonizing peptide attenuates colitis in mice." (PMID 33767714, 2021). "Thus, similar to TREM-1, TREM-2 may foster the progression of colitis-associated cancer by controlling epithelial proliferation during colonic injury and inflammation." (PMID 31546668, 2019). "However, precisely how TREM-1 deficiency mediates its protective role against colitis was not delineated." (PMID 31189465, 2019). "The observations made in the acute DSS model of colitis raised our interest whether Trem1−/− mice would also be able to control bona fide microbial infections, in particular, since maximal silencing of TREM-1 by a siRNA approach had proven deleterious in a fecal peritonitis model." (PMID 24453980, 2014). "Blocking TREM-1 with this antagonist peptide (LP17) also attenuated clinical severity and histopathologic damage in experimental model of murine colitis." (PMID 38881893, 2024). "In experimental mouse models of colitis and patients with IBD, intestinal TREM-1 expression was upregulated and correlated with disease severity." (PMID 38881893, 2024). "Similar to human patients, murine colitis models show intense accumulation of Ly6Chi monocytes, which also produce high levels of IL-1β, TNF-α, IL-6, IL-12, and express high level of TREM1 and respond in a highly pro-inflammatory manner to TLR stimulation." (PMID 34912006, 2022). "The top 3 predicted upstream regulators in inactive extensive colitis were miR-155-5p, SOCS1, and TREM1, regulating CXCL2 and SOCS1; CXCL2 and SOCS1; and CXCL2, HES4, and TIFA, respectively." (PMID 32731480, 2020). "Conversely, when animals are administered a TREM-1 antagonist (LP17 peptide), either before or after colitis induction, pathological alterations and inflammatory mediators are suppressed." (PMID 31546668, 2019). "To determine the levels of various cytokines known to aggravate DSS-induced colitis, we used real-time PCR to screen colons from DSS-treated WT and TREM-1 KO mice for mRNA levels of inflammatory cytokines." (PMID 31189465, 2019). "This is consistent with what observed in another model of experimental colitis (RAG2−/− mice with adoptive transfer of CD4+ CD25− CD45RBhi T cells), where both colonic TREM-1 mRNA and serum sTREM-1 levels are markedly increased." (PMID 31546668, 2019). "Our findings demonstrate that Trem1−/− mice not only show a highly attenuated CD4+ T cell- and DSS-induced colitis but also display significantly reduced lesion size and diminished morbidity during infections with L. major and influenza virus, respectively." (PMID 24453980, 2014). "In both a T-cell transfer model of colitis in RAG2−/− mice and in C57BL/6 mice with DSS-induced colitis, TREM-1 mRNA and protein have been shown to be significantly up-regulated, a finding that preceded the appearance of histological signs of the disease." (PMID 25347935, 2014). "Bulk RNA sequencing of colon tissues from FLNAR and FLNAQ animals on day 10 of DSS-induced colitis (the peak of disease) confirmed that FLNAR mice had less inflammation as indicated by a reduced expression of inflammatory genes (Il1b, Cxcl3, Cxcl2, or Trem1)." (PMID 40471139, 2025).
colitis (continued). "Importantly, adoptive transfer of WT macrophages into DSS-treated TREM-1 KO mice significantly reduced colitis and tissue damage in comparison to TREM-1 KO mice that received TREM-1 KO macrophages." (PMID 31189465, 2019). "Mortality was consequently increased, and no TREM-1 KO mouse was able to recover from DSS-induced acute colitis over days 5–9." (PMID 31189465, 2019). "Furthermore, administration of an antagonist TREM-1 peptide (LP17), even after the establishment of colitis, decreased disease severity as evaluated by the extent of colon shortening and by milder alterations in colon histopathology." (PMID 25347935, 2014). "Due to the peculiar activities of TREM-1 and TREM-2 in controlling bacterial infection, the functional role of these two receptors has also been studied in IBD patients and in experimental models of colitis." (PMID 25347935, 2014). "Accordingly, the degree of protection from colitis was not much higher in Trem1−/− mice compared to mice that were treated with the antagonistic LP17 peptide in our previous study." (PMID 24453980, 2014). "For example, we found that Trem1-KO mice had higher DAI values in normal condition without colitis." (PMID 33767714, 2021). "Additionally, we can postulate that the upregulated TREM-1 levels in IBD may be due to impaired neutrophil function, neutrophil recruitment, or TLR signaling, but this requires further elucidation of the mechanisms by which α-TREM-1 alleviates colitis as well as its role in IBD pathogenesis." (PMID 33767714, 2021). "We have previously demonstrated a substantial accumulation of TREM-1 expressing macrophages in the inflamed, but not healthy intestinal mucosa of patients with IBD and of mice with experimental colitis." (PMID 24453980, 2014).
hepatocellular carcinoma (34 papers, 2013 to 2025). A malignant tumor that arises from hepatocytes. "It is important to remark that TREM-1 expression in TAM has been associated to resistance to PD-L1 blockade in hepatocellular carcinoma." (PMID 38195888, 2024). "In human oncology, high levels of TREM-1 and/or its soluble form have been associated with poorer survival data in several solid malignancies, especially in hepatocellular carcinoma and lung cancer." (PMID 35875168, 2022). "From the perspective of the tumor microenvironment, TREM1+ tumor-associated macrophages (TAMs) are abundant in the hypoxic environment of hepatocellular carcinoma." (PMID 33297569, 2020). "Recent studies showed that TREM-1 is also associated with lung cancer and hepatocellular carcinoma development." (PMID 31275318, 2019). "MCP-1 has been implicated in higher recurrence and worse bladder cancer prognosis by mediating tumor invasion, while TREM-1 has been implicated in activation of Kuffner cells in hepatocellular carcinoma." (PMID 24733360, 2014). "Additionally, TREM-1 upregulation has been implicated in non-alcoholic fatty liver disease, hepatocellular carcinoma, neurodegenerative disorders, and neonatal sepsis." (PMID 41226426, 2025). "Accordingly, TREM1 expression and activation has been reported to be linked to pathological conditions including rheumatoid arthritis, inflammatory bowel disease, and liver diseases including hepatocellular carcinoma." (PMID 31260499, 2019). "In addition, TREM-1 deficiency attenuated Kupffer cell activation by down-regulating cytokine production and signal induction and controlled the development of hepatocellular carcinoma." (PMID 31509552, 2019). "The plasma levels of soluble TREM1(sTREM1) were significantly elevated in patients with renal cell carcinoma, hepatocellular carcinoma and non-small cell lung cancer." (PMID 39744496, 2025). "Our study identifies TREM1 as a critical regulator of liver cancer stem-like cells (LCSLCs) in hepatocellular carcinoma (HCC), exhibiting distinct tumor-intrinsic functions beyond its well-established immunomodulatory roles in the tumor microenvironment." (PMID 40677705, 2025). "Studies on murine hepatocellular carcinoma models have demonstrated that HMGB1 binds to TREM-1 on necrotic hepatocytes, with an affinity (Kd) of =35.4 μM." (PMID 41226426, 2025). "Immunoprecipitation studies in hepatocellular carcinoma cells have demonstrated that TREM1 forms a complex with TLR4 to activate downstream signaling." (PMID 41394801, 2025). "High TREM1 expression levels in lung adenocarcinoma and hepatocellular carcinoma were suggested to be independent predictors of tumor progression and poor prognosis." (PMID 38370418, 2024). "A study has shown that TREM1 is highly expressed in hepatocellular carcinoma tissue and significantly promotes the proliferation and invasion of HCC cells." (PMID 38914803, 2024). "TREM-1 induces inflammation and lipid accumulation in human hepatoma cell line HepG2 and primary mouse hepatocytes by activating the PI3K-AKT pathway." (PMID 35487953, 2022). "More recently, TREM-1 signaling was reported to directly promote immunosuppression in hepatocellular carcinoma and abrogate immune checkpoint inhibition." (PMID 34956864, 2021). "Moreover, previous studies have found that TREM1 dramatically promotes proliferation and invasion in Hepatocellular Carcinoma (HCC) and TREM1 expression has been associated with poor survival in HCC patients." (PMID 33323544, 2020). "In hepatocellular carcinoma, TREM-1 deletion decreased diethylnitrosamine-induced liver cancer by attenuating Kupffer cell activation." (PMID 31275318, 2019).
hepatocellular carcinoma (continued). "Previous studies on the involvement of TREM-1 in hepatocellular carcinoma and lung cancer have suggested a role for TREM-1-expressing macrophages." (PMID 29093489, 2017). "Investigation of potential schizophrenic pathways with the IL-2/TREM-1 pathway reveals possible complexes or drugs responsible for novel treatment of schizophrenia and hepatocellular carcinoma." (PMID 24564241, 2013). "However, the specific immune cell localization of TREM1 in hepatocellular carcinoma tissue needs further study." (PMID 38914803, 2024). "A TREM1 inhibitor could sensitize tumors to immunotherapy in a model of hepatocellular carcinoma by synergistically reversing immunosuppression and reactivating effector T cells to exert tumor cell cytotoxicity." (PMID 38370418, 2024). "In conclusion, CCL7 derived from TREM1+ TAMs can promote hepatocellular carcinoma metastasis." (PMID 38914803, 2024). "Although the function of TREM1 in cancer is still unclear, TREM1 expression promotes tumorigenesis and supports tumor growth in various tumor models, including intestinal, pancreatic, and lung cancers and hepatocellular carcinoma." (PMID 37651197, 2023). "However, it is now well known that TREM-1 is highly expressed in some tumoral tissues, as hepatocellular carcinoma and lung carcinoma." (PMID 35875168, 2022). "Moreover, TREM-1 was recently shown to inhibit anti-tumor immunity in a model of hepatocellular carcinoma." (PMID 34956864, 2021). "Recent studies have shown a close link between TREM-1 and cancer, as TREM-1 is selectively expressed on tumor-associated macrophages (TAMs) in non-small cell lung cancer, activates in the liver Kupffer cells, and promotes the progression of hepatocellular carcinoma." (PMID 37217993, 2023). "Functional experiments involving hepatocellular carcinoma (HCC) have suggested that TREM-1 promotes proliferation, increases invasiveness and inhibits apoptosis of HCC cells." (PMID 34122331, 2021). "In non-small cell lung cancer (NSCLC) and hepatocellular carcinoma (HCC), TREM-1 protein levels significantly correlate with poorer overall and disease-free survival." (PMID 34956864, 2021). "Likewise, a separate study demonstrated that TREM1 plays a significant role in influencing the growth, progression, and prognosis of hepatocellular carcinoma (HCC) and lung cancer." (PMID 39149674, 2024). "More recently, using a murine model of hepatocellular carcinoma, HMGB1 released from necrotic hepatocytes was found to bind TREM-1 using immunoblotting and SPR, with a binding KD of 35.4 x 10-6 M." (PMID 35784361, 2022). "In this study, multivariate Cox regression was used to construct a prognostic biomarker model of hepatocellular carcinoma consisting of two protein-coding genes (GTPBP4, TREM-1) and one lncRNA (LINC00426)." (PMID 33204302, 2020). "Recently, several studies have reported that TREM1, another member of the TREM family, exerted tumor promoting effects on human malignancies including lung cancer, colon cancer and hepatocellular carcinoma (HCC)." (PMID 26506595, 2016). "Wu and colleagues developed a TREM-1 knockout (KO) mouse and demonstrated that TREM-1 was essential for the activation of Kupffer cells in the diethylnitrosamine model of hepatocellular carcinoma and contributed to chronic liver damage." (PMID 25505454, 2014). "Taken together, TREM1 and CCL7 are the proven cancer-promoting factors of hepatocellular carcinoma." (PMID 38914803, 2024). "In research on hepatic carcinoma, TREM-1 expressing TAMs exhibited as the fundamental bridge to enhance CCR6+ Foxp3+ Treg accumulation, which disabled targeting PD-1 therapy, while the blockade on TREM-1+ TAMs revived the therapeutic activity." (PMID 33505964, 2020).
hepatocellular carcinoma (continued). "Using a schizophrenia-hepatocellular carcinoma network, the authors found that some schizophrenia candidate genes (SIRPB1, SYK, and LCK) and genes mediating the immune responses in the etiology mechanism of schizophrenia (IL-2 and TREM-1/DAP12) may also function as tumor-suppressor genes." (PMID 29254248, 2017).
rheumatoid arthritis (30 papers, 2012 to 2025). A chronic, systemic autoimmune disorder characterized by inflammation in the synovial membranes and articular surfaces. "Interestingly, one study showed that higher physical activity levels were associated with the inhibition of the TREM1 signaling pathway in whole blood from adults with rheumatoid arthritis." (PMID 40881686, 2025). "In the samples of rheumatoid arthritis synovium, the expression of TREM-1 is upregulated, and increased numbers of TREM-1-positive cells are observed." (PMID 37168858, 2023). "TREM-1, which is expressed on monocytes and/or macrophages and neutrophils, functions as an inflammation amplifier and plays a role in the pathogenesis of rheumatoid arthritis (RA)." (PMID 36012120, 2022). "Dan reported that TREM1 is a therapeutic target to inhibit the inflammatory response in rheumatoid arthritis." (PMID 33446277, 2021). "It was consistent with a previous study that triptolide inhibited the inflammatory response in rheumatoid arthritis by modulating the TREM-1 signaling pathway." (PMID 31885496, 2019). "Increasing evidences have verified that the levels of TREM-1 and sTREM-1 were remarkably increased in sepsis and autoimmune diseases, including rheumatoid arthritis, systemic lupus erythematosus, and primary antiphospholipid syndrome." (PMID 31885496, 2019). "In the main pathways of AP, those with high ratios included TREM1 signaling, complement system, altered T-cell and B-cell signaling in rheumatoid arthritis, and B-cell development." (PMID 29679058, 2018). "Other groups also showed positivity for TREM-1 on myelomonocytic cells infiltrating synovial joints of rheumatoid arthritis patients." (PMID 28936211, 2017). "The aim of this study was to determine whether rheumatoid arthritis synovial fibroblasts (RASF) promote the expression of TREM-1 in monocytes and its potential regulatory mechanism." (PMID 31287012, 2019). "Gene ontology analysis of the transcriptome revealed altered expression levels of genes related to inflammatory response-related canonical pathways such as triggering receptor expressed on myeloid cell 1 (TREM1) signalling, neuroinflammation, and rheumatoid arthritis." (PMID 30151012, 2018). "Of note, most of the modulated pathways were immune-related (e.g., altered T cell and B cell signaling in rheumatoid arthritis, dendritic cell maturation and Toll-like receptor and TREM1 signaling), suggesting the suppression of immune function at this early time point." (PMID 26021444, 2015). "There were a number of pathways that were significant by 1 hour and remained significant following both LPS and Pam3CSK4 stimulations: “TNFR2 signalling”, “TREM1 signalling”, Altered T cell and B Cell signalling in Rheumatoid arthritis” and “Dendritic cell maturation” pathways." (PMID 24842522, 2014). "Other studies demonstrated that TWG modulated triggering receptors expressed in the myeloid cell (TREM)-1 signaling pathway to inhibit the inflammatory response in rheumatoid arthritis (RA), yielding a good effect." (PMID 30021637, 2018). "Triggering receptor expressed on myeloid cells 1 (TREM‐1) is critically involved in the pathogenesis of rheumatoid arthritis (RA)." (PMID 28382703, 2017). "Recent studies indicate that TREM-1 and its signaling adapter DAP12 play a role in rheumatoid arthritis." (PMID 40362275, 2025). "This study investigated whether serum levels of TREM-1 and PGLYRP1 correlate with periodontitis in rheumatoid arthritis (RA) patients." (PMID 33536478, 2021).